RNU6-375P (RNA, U6 small nuclear 375, pseudogene)
Gene: Small nuclear RNA gene on chromosome 22 (41,168,217 to 41,168,316, forward strand). Ensembl gene ENSG00000252859.
Homologues: Orthologues: chimpanzee U6 (99% identical), macaque U6 (92% identical), pig U6 (63% identical), guinea pig U6 (62% identical), pig U6 (59% identical), rat LOC120099053 (53% identical). Paralogues in human: RNU6-836P (77% identical), RNU6-593P (73% identical), RNU6-753P (73% identical), RNU6-896P (73% identical), RNU6-940P (73% identical), RNU6-1085P (72% identical), RNU6-1099P (72% identical), RNU6-1145P (72% identical), RNU6-116P (72% identical), RNU6-181P (72% identical), RNU6-211P (72% identical), RNU6-330P (72% identical), and 1286 more.